INS (insulin)
Diseases named in the same sentence as INS in open-access papers (continued):
Sharing a sentence is not in itself a finding about the gene and the disease.
Insulin resistance (continued). "They exhibit increased abdominal subcutaneous and visceral adiposity, adipose insulin resistance and impaired insulin secretion, and an increased incidence of T2DM." (PMID 37834765, 2023). "Insulin resistance is defined as a compromised physiologic response of target tissues, predominantly the muscle, liver and adipose tissue, to insulin stimulation." (PMID 36838411, 2023). "Impaired insulin secretion or insulin resistance interferes with lipolysis, augmenting circulating fatty acids." (PMID 38055691, 2023). "Impairment of insulin signaling by ER stress can hinder adipocyte differentiation, ultimately contributing to insulin resistance." (PMID 38140341, 2023). "Maintaining lower–normal glucose levels with lower insulin and IGF-1 levels is associated with improved health outcomes, decreasing risk of insulin resistance and T2DM, reducing chronic diseases, and also improving longevity and healthy ageing." (PMID 37958602, 2023). "Inflammation, dysfunction, and elevated OS levels lead to insulin signaling cascade disorder and are important triggers of insulin resistance." (PMID 37077347, 2023). "Their adipose insulin resistance index (fasting serum insulin times serum FFA) had a 31.2% reduction at the end of the Mifepristone administration." (PMID 38260129, 2023). "The homeostasis model of insulin resistance (HOMA-IR) measures the level of insulin and glucose in the blood and has been widely used, especially in epidemiological and clinical studies." (PMID 37241071, 2023). "Later, however, insulin resistance developed over time, but insulin secretory function and compensatory pancreatic β cell proliferation were impaired in multiparous mice." (PMID 37903900, 2023). "Similar results were observed for fasting serum insulin and homeostasis model assessment of insulin resistance (HOMA-IR) levels, with a significant decrease in groups G2 and G3 (p<0.05)." (PMID 38313181, 2023). "Insulin resistance is due to decreased tissue sensitivity to insulin and the inability of the pancreas to secrete sufficient insulin for blood glucose regulation for physiological functions." (PMID 36839456, 2023). "The results showed that DEHP exposure led to impaired regulation of the GLUT2 gene and insulin signal transduction, leading to decreased glucose tolerance, insulin resistance, and hyperglycemia." (PMID 37367903, 2023). "This reduction in GDM is likely mediated through decreased insulin resistance as Jacubowicz and co-workers showed improved insulin sensitivity in PCOS women treated with metformin (1000-2000mg daily) compared to those who did not receive treatment." (PMID 38027110, 2023). "And dopamine D2/3 receptor inhibition at the ventral striatum results in diminished insulin sensitivity and in concert decreased mesolimbic dopamine activity leads to insulin resistance." (PMID 36993818, 2023). "Insulin resistance was observed in all insulin-resistant groups as evidenced by reduced pAkt expression following insulin stimulation." (PMID 37367923, 2023). "Sustained efforts to map signaling topology and function will reveal how signaling alterations we identified in insulin resistance are embedded within and shape the insulin signaling network." (PMID 36808134, 2023). "In this study, we examined insulin resistance in early adulthood and insulin signaling in skeletal muscle using a novel FGR rat model." (PMID 36649006, 2023). "In this way, PGC-1α is involved in improving insulin signaling as the reduction of PGC-1α in skeletal muscle cells was suggested to induce insulin resistance." (PMID 38027557, 2023). "Inadequate secretion of cytokines such as TNF-α and IL-10 strengthens insulin resistance in db/db mice, resulting in adipocytes’ increased insensitivity to insulin." (PMID 38202328, 2023). "It has been observed that consuming lean seafood and fish improves insulin sensitivity and lowers insulin resistance in individuals with insulin resistance." (PMID 37009872, 2023).
Insulin resistance (continued). "Sustained activation of mTOR in AD also disables its activation by insulin, contributing to insulin resistance." (PMID 37457922, 2023). "“Insulin resistance”, “inflammation”, and “sensitivity to insulin” are common mechanisms in the field of prediabetes." (PMID 36908460, 2023). "In order to evaluate the effect of collagen peptides on insulin resistance development, we assessed the levels of glucose, insulin, and glycated hemoglobin (HbA1c)." (PMID 36864815, 2023). "In another study, adenoviral-mediated expression of SOCS1 in mouse liver blocked insulin signaling by ubiquitin-mediated degradation of insulin receptor substrates 1 and 2, resulting in insulin resistance." (PMID 36609306, 2023). "Insulin resistance can in part be attributed to abnormal hepatic insulin processing; this would otherwise physiologically regulate glucose and lipid metabolism." (PMID 37377968, 2023). "IDV inhibited insulin-stimulated glucose uptake at pharmacologically relevant drug levels in cultured adipocytes, which provided a direct explanation for peripheral insulin resistance." (PMID 37175645, 2023). "A significant difference in the amount of FI, HOMA-IR, the rate of HOMA-IR > 4.5, the rate of individuals with insulin resistance, fasting glucose/fasting insulin (FG/FI), and the rate of FG/FI > 4.5 were found among RPL patients compared to controls." (PMID 36604717, 2023). "Fasting plasma glucose and insulin levels are important parameters used to judge insulin resistance." (PMID 36655087, 2023). "The primary defect in T2D is defective glucose-induced insulin secretion, which is made worse in the presence of general insulin resistance, a condition that frequently accompanies the development of the syndrome of T2D, obesity, and hyperlipidemia." (PMID 36834496, 2023). "Insulin is rarely measured in routine clinical practice, precluding identification of early insulin resistance until later, more advanced stages of the type 2 diabetes disease spectrum." (PMID 38115031, 2023). "Atorvastatin increased insulin resistance by 8% and insulin secretion by 9% compared to the baseline measurements." (PMID 37795366, 2023). "Suppression of the insulin signaling pathway can have various consequences, including the lowering of the response to insulin, characteristic of the onset of insulin resistance and observed in this study." (PMID 37512524, 2023). "Insulin resistance is the inability of a cell, tissue, or organism to respond appropriately to a given dose of insulin." (PMID 37781697, 2023). "Activation of the Hippo signaling pathway in hyperglycemic states induces proliferation and differentiation of pancreatic β-cells, increasing glucose uptake and utilization, thereby reducing insulin resistance, and improving insulin secretion." (PMID 36891054, 2023). "Total cholesterol, LDL-c, triglycerides, fasting glucose, glycated hemoglobin, insulin, and insulin resistance were reduced in both groups during the 1-year follow-up (p < 0.05)." (PMID 37591922, 2023). "Insulin resistance (IR), a pathophysiological condition of decreased sensitivity and responsiveness to insulin, has been recognized as a characteristic of metabolic syndrome (MS) and atherosclerosis." (PMID 37845738, 2023). "Type 2 diabetes (T2D) is an age-related disease characterized by a decrease in β-cell mass and function with a failure to compensate for the high insulin demand during insulin resistance." (PMID 37441495, 2023). "We found that haemoglobin A1c, fasting blood glucose, fasting insulin, homeostasis model assessment of insulin resistance and thioredoxin interaction protein were enhanced, while HOMA-β was reduced with the decrease of 25(OH)D concentration." (PMID 36874363, 2023). "The oxidative damage not only plays a role in the development of kidney injury but also hinders the proper functioning of insulin signaling pathways, thereby worsening insulin resistance." (PMID 37868469, 2023).
Insulin resistance (continued). "Increased insulin resistance, reduced insulin secretion from the pancreas, and glucose intolerance were observed in patients with pancreatic cancer as well as in animal models, and are associated with higher cancer mortality in a longitudinal study." (PMID 36831310, 2023). "Nicotine increases cortisol, catecholamines and growth hormone secretion, hormones that counteract the actions of insulin, contributing to insulin resistance." (PMID 37347387, 2023). "Insulin resistance (IR) means the diminished or impaired sensitivity to endogenous and exogenous insulin in insulin-dependent organs and tissues." (PMID 36997935, 2023). "Type 2 diabetes is traditionally characterized by insulin resistance/reduced systemic insulin sensitivity, and islet β-cell dysfunction." (PMID 38202328, 2023). "Regular exercise activates AMPK to improve mitochondrial homeostasis, muscle metabolic capacity, increase blood glucose and improve metabolic disorders, and reduce blood glucose, blood insulin levels and insulin resistance in obesity and type 2 diabetes." (PMID 37964253, 2023). "Ang II alters glucose homeostasis by inhibiting insulin signal transduction, reducing glucose uptake, increasing insulin resistance, and destroying pancreatic β cells by inducing oxidative stress." (PMID 37763076, 2023). "Insulin resistance (IR) is a pathological condition underpinned by reduced glucose uptake in response to physiological insulin levels and tissue responses to insulin-mediated cellular actions." (PMID 37635963, 2023). "In this model, phospho-Akt/Akt levels were significantly increased by the insulin challenge (100 nM), whereas this response was abated after chronic treatment with high-concentration insulin, thus showing that insulin resistance was successfully achieved." (PMID 36901549, 2023). "As mentioned, several lifestyle factors have been observed to lower levels of fasting and postprandial insulin as well as of insulin resistance." (PMID 37854186, 2023). "Insulin resistance reduces glucose uptake in insulin-sensitive tissues, including skeletal muscle, liver, and adipose tissue." (PMID 37298440, 2023). "We investigated the impact of AE on serum levels of FNDC-5, glucose, insulin, and the homeostasis model assessment of insulin resistance (HOMA-IR)." (PMID 36982812, 2023). "In the childhood and pubertal period, there is a physiological increase in insulin resistance and high insulin levels which usually normalize with the end of puberty." (PMID 36767041, 2023). "Women with insulin resistance then need to achieve strict glycemic control to avoid pregnancy complications resulting from hyperglycemia, and insulin is proven to reduce complications for both the mother and the fetus." (PMID 37409227, 2023). "We also conclude that youth-onset T2D is influenced by risk factors in multiple biological pathways, contributing to (at minimum) beta-cell development, insulin secretion, and obesity-related insulin resistance." (PMID 37292813, 2023). "Nevertheless, it is well established that ovarian cells from PCOS subjects retain insulin sensitivity, even in those patients showing insulin resistance, as both insulin and hyperinsulinemia still stimulate ovarian androgen production in PCOS." (PMID 37047265, 2023). "Insulin resistance (IR) occurs when cells become insensitive to insulin, leading to a buildup of glucose and insulin in the blood." (PMID 37892657, 2023). "Insulin resistance, defined as a reduced sensitivity of body cells to insulin, is a common disorder among patients with metabolic syndrome, as well as with frailty syndrome." (PMID 37110134, 2023). "One of the most serious problems caused by lowered interstitial fluid pH is the development of insulin resistance via decreased binding affinity of insulin to its receptor." (PMID 37238649, 2023).
Insulin resistance (continued). "It is now generally accepted that chronic inflammation, insulin resistance, hyperinsulinemia, hyperglycemia, and abnormalities in the insulin and insulin-like growth factor (IGF) axis contribute to the disease association between these two conditions." (PMID 36672448, 2023). "Nevertheless, this mechanism alone does not fully elucidate why the group with FA, whilst reporting the lowest plasma insulin and insulin resistance, still exhibits higher frequencies of reactive hypoglycemia with respect to the other groups." (PMID 37726785, 2023). "T2DM results from a combination of insulin resistance and impaired insulin secretion by ß pancreas cells." (PMID 38406782, 2023). "The key to the protective effect of DNLA in DM is to regulate the insulin signaling pathway and improve insulin resistance." (PMID 37009462, 2023). "With regard to glucose metabolism, seven studies measured levels of fasting insulin and fasting glucose and conducted the test of homeostatic model assessment of insulin resistance (HOMA-IR)." (PMID 36925956, 2023). "Result from this supported earlier research in that LETZ-induced PCOS in mice led towards increased levels of insulin, a sign of insulin resistance, a critical feature of metabolic disorders (MD’S)." (PMID 37670876, 2023). "Social jet lag is related to a lower HDL-cholesterol level, higher triglycerides, higher fasting plasma insulin, insulin resistance, and adiposity." (PMID 36984810, 2023). "“Insulin resistance”, “inflammation”, and “sensitivity to insulin” were popular pathological mechanisms in prediabetes." (PMID 36908460, 2023). "The main characteristic of T2D is insulin resistance (IR), a pathological state in which there is an altered response to insulin by insulin-sensitive tissues, mainly the skeletal muscle, adipose tissue, and liver." (PMID 37653931, 2023). "Insulin resistance is defined as the inability of insulin to effectively regulate the uptake and/or utilization of glucose by insulin-sensitive tissues and organs." (PMID 36979669, 2023). "In the context of T2D, IL-6 and TNF-α are known to be upregulated, contributing to insulin resistance, impaired insulin-mediated glucose uptake in peripheral tissues, and endothelial dysfunction in T2D." (PMID 37892970, 2023). "In obesity, the body’s adipose tissue secretes proinflammatory cytokines and adipokines, which can impair insulin signaling and promote insulin resistance." (PMID 37047308, 2023). "Insulin resistance (IR), the insensitivity of insulin-dependent tissues to the hormone action, is a key process linking childhood obesity to cardiovascular risk factors by increasing the risk of coronary heart disease." (PMID 36670674, 2023). "Insulin resistance is fasting insulin levels of more than 20 mIU/mL and postprandial insulin levels of more than 55 mIU/mL." (PMID 37954695, 2023). "The state of insulin resistance commands enhanced insulin secretion to recompense; hence, fasting plasma insulin is in high concentrations." (PMID 37664840, 2023). "Both noncirrhotic NASH and cirrhotic NASH patients were insulin resistant as indicated by homeostatic model assessment for insulin resistance but the cirrhotic NASH displayed higher levels of circulating insulin." (PMID 36737040, 2023). "TXNIP is a mediator of insulin resistance in the liver, skeletal muscle, and adipose tissue and impaired pancreatic beta-cell insulin secretion." (PMID 38292764, 2023). "The potential of chromium to mitigate insulin resistance and enhance insulin sensitivity through cellular receptors underscores its significance." (PMID 38024820, 2023). "Several studies have shown positive associations between CKD and FPG, OGTT, and HbA1c, as well as fasting insulin level, homeostasis model assessment of insulin resistance (HOMA-IR), and HOMA-β." (PMID 37564380, 2023). "Insulin resistance is accompanied by compensatory insulin release from the pancreatic beta cells, which eventually leads to beta cell exhaustion and dysfunction." (PMID 37623520, 2023).
Insulin resistance (continued). "In summary, this study validates C2-cer as a convenient tool to decipher mechanisms by which SFA mediate insulin resistance in muscle cells since it increases endogenous ceramide levels responsible of insulin resistance." (PMID 37178918, 2023). "Adiponectin functions as an insulin sensitizer, overcoming the insulin resistance that plays a role in the pathogenesis of ED." (PMID 37626670, 2023). "In another small study in patients with gout and insulin resistance, taking metformin at a dose of 1500 mg/day was accompanied by a statistically significant decrease in serum UA level, fasting insulin concentration, and HOMA insulin resistance index." (PMID 37833606, 2023). "Insulin resistance reduces the response of the body’s cells to insulin, which can stimulate the liver to synthesize more fatty acids and result in the accumulation of fat in the liver, exacerbating the progression of NAFLD." (PMID 38062499, 2023). "In individuals with obesity and overweight there is an increase in insulin levels and insulin resistance, which promotes vasodilation due to stimulation of nitric oxide (NO) release from endothelial cells." (PMID 37249452, 2023). "Although some patients have hyperinsulinemia or insulin resistance, they are treated with insulin or insulin analogs when treatment with adequate doses of other available anti-diabetic drugs does not lead to the target optimized blood glucose control." (PMID 37324170, 2023). "These factors can impair insulin action and induce insulin resistance by interfering with insulin receptor function or downstream signaling components." (PMID 37680899, 2023). "The FEV1: FVC% was negatively correlated with BMI (r=0.53), WHR (r=0.50), glucose (r=0.68), insulin (r=0.68), Insulin resistance (r=0.80), and positive correlation with Vit B12 (0.73)." (PMID 37362491, 2023). "Insulin resistance is a key feature of T2D, and skeletal muscle is the primary site of insulin-stimulated glucose uptake." (PMID 37511225, 2023). "In insulin resistance, the inhibitory effect of insulin on NOTCH was attenuated due to the impairment of insulin signaling, thereby causing elevated ZFYVE28 expression." (PMID 37884540, 2023). "In people living with obesity, who have severe insulin resistance (IR) that is compensated by β-cell insulin hypersecretion, post-prandial ClI is consequently reduced and acts as an independent determinant of lower β-cell function over time." (PMID 37834412, 2023). "In this review, we discuss insulin resistance pathophysiology and the use of dynamic exogenous insulin administration in a manner consistent with more normal insulin secretion periodicity to reverse insulin resistance." (PMID 37446104, 2023). "Insulin resistance likely leads to elevated fasting insulin which upregulates NPR‐C and results in increased NP clearance." (PMID 36905117, 2023). "Because insulin resistance and obesity play a crucial role in MS pathogenesis, we conducted a statistical analysis of metabolic syndrome, and variables such as insulin levels, BMI, and metformin treatment." (PMID 37960185, 2023). "Various insulin resistance inducers can be used in vitro, including chronic insulin exposure, dexamethasone, proinflammatory cytokines, adipokines, and hypoxia." (PMID 36714242, 2023). "Obesity and increased content of visceral adipose tissue are associated with several metabolic changes—e.g., hyperinsulinemia, insulin resistance—or increased oxidative stress, altering the insulin–IGF axis." (PMID 37048534, 2023). "In insulin resistance, co-causative factors including glucotoxicity, lipotoxicity, and inflammation selectively impair PI3K-dependent insulin signaling pathways, thereby inducing the atherogenic process and leading to the occurrence of ASCVD." (PMID 37674809, 2023).